TNF (tumor necrosis factor)
Diseases named in the same sentence as TNF in open-access papers (continued):
Sharing a sentence is not in itself a finding about the gene and the disease.
Alzheimer disease (continued). "Tumor necrosis factor alpha (TNF-α), a proinflammatory cytokine, is upregulated in several neurodegenerative disorders including multiple sclerosis, Parkinson’s disease, Alzheimer’s disease and in optic nerve microglia and astrocytes in glaucoma patients." (PMID 20029655, 2009). "Notably, in chronic inflammation, such as Alzheimer’s disease, both 5-HT2b and BDNF levels are elevated, paradoxically contributing to neurotoxicity as BDNF released near amyloid plaques promotes TNF-α and glutamate release." (PMID 41511349, 2025). "Alzheimer’s disease, like other neurodegenerative diseases discussed here, is marked by elevated TNF levels, but TNF inhibition fails to treat the disease." (PMID 40869160, 2025). "For example, inflammatory genes such as TNF and TGFB1 (both annotated as being important to myocardial infarction) are not included in the list of genes associated with Alzheimer’s disease on DisGeNET." (PMID 40163580, 2025). "In contrast, RUT in large dose mitigated neuroinflammation by significantly reducing TNF-α and IL-1β levels, which is consistent with previous reports on RUT in neurodegenerative diseases including Alzheimer’s disease, Parkinson’s disease, and Huntington’s disease." (PMID 38512652, 2024). "Subsequent experiments could investigate the impact of TNFα regulation on NOX4 in astrocytes, exploring its influence on iron-induced cell death and its role in Alzheimer’s disease." (PMID 38956702, 2024). "In Alzheimer’s disease, amyloid beta and tau proteins activate the p38 MAPK pathway in both microglia and astrocytes, resulting in the sustained production of pro-inflammatory cytokines such as IL-1β and TNF-α." (PMID 39852123, 2024). "Neuroinflammation initiated by cytokines, including TNF-α and IL-1β, may be involved in BBB dysfunction and thereby promote the advancement of Alzheimer’s disease by fostering amyloid-β peptide accumulation." (PMID 39641002, 2024). "Although there are no other studies investigating the association between the TNF-alpha polymorphism rs1800630 and MS, other studies are looking at this polymorphism and its potential impact on similar diseases such as AMD and Alzheimer’s disease." (PMID 38999258, 2024). "Sterubin, a flavonoid compound, has been identified as a neuroprotective agent capable of reducing the expression of inflammatory biomarkers (such as IL-6, IL-β, and TNF-α) as well as oxidative stress markers (such as SOD and MDA) in order to prevent chemically-induced Alzheimer’s disease in rats." (PMID 37801482, 2023). "In Alzheimer’s Disease, increased IL-21 levels lead to increased expression of MHC II in spleen Mφ and secretion of a large number of pro-inflammatory cytokines such as IL-18, TNFα and IL-1β." (PMID 37628738, 2023). "For example, plasma levels of IL-6, but not TNF-α, increased after a 16-week duration of moderate-to-high-intensity aerobic physical exercise in Alzheimer’s disease patients." (PMID 36156182, 2022). "TSAIII up-regulated the acetylcholine contents, inhibited the AChE activity and decreased the expression of TNF-α and IL-1β in scopolamine-treated mice brain models, meaning that TSAIII may be across the blood–brain barrier (BBB) in Alzheimer’s disease." (PMID 36611961, 2022). "Cytokine-induced neuroinflammation, such as the tumor necrosis factor-α (TNF-α) and interleukin-1β (IL-1β), appear to play a role in BBB dysfunction and contribute to the progression of Alzheimer’s disease (AD) by contributing to amyloid-β (Aβ) peptide accumulation." (PMID 36142143, 2022). "In addition, in a model of Alzheimer’s disease in mice, treatment with hesperidin (40 mg/kg, 90 days intragastric) increased HO1 and decreased levels of TNFα, CRP, NF-κB and MCP1, suppressing oxidative stress and inflammation." (PMID 33799833, 2021).
Alzheimer disease (continued). "Greater levels of TNF degradation products in plasma were observed herein but a recent review concludes there is no increase in circulating TNF- α in Alzheimer’s disease perhaps indicating a role for turnover in the regulation of TNF levels." (PMID 34182925, 2021). "In Alzheimer’s disease cases, IL-15, IL-1β, IL-6, TNF-α, and IL-8 were higher in those with than without infection." (PMID 33723589, 2021). "An intriguing candidate for specifically inhibiting soluble TNFα without impairing protective juxtacrine TNFα signaling is the brain-permeant biologic XPro1595, currently in phase 1b testing in patients with Alzheimer’s disease (NCT03943264)." (PMID 34961522, 2021). "Furthermore, elevated systemic TNF-α produces acute cognitive dysfunction and inhibition TNF-α trafficking prevents cognitive decline in an Alzheimer’s disease mouse model." (PMID 32059688, 2020). "When we included participants with different severity of Alzheimer’s disease, the peripheral TNF – α levels were not significantly higher than controls." (PMID 30104698, 2018). "An important pro-inflammatory cytokine TNF-α, which is responsible for granuloma formation and controlling M. tb infection in macrophages were lower in HIV-1 infected individuals compared to healthy individuals and individuals with Alzheimer's disease." (PMID 27335804, 2016). "In models of Alzheimer disease produced by overexpression of APP/PS1 or human APP, CX3CR1 knockout results in decreased levels of pro-inflammatory cytokines Tumor Necrosis Factor (TNF) and monocyte chemotactic protein 1 (CCL2) but increased Interleukin 1-beta (IL1β)." (PMID 26469270, 2015). "According to more recent findings, bilobalide has an excellent anti-inflammatory effect and could inhibit TNF-α expression in the frontal cortex and hippocampus CA1 of Alzheimer’s disease model rats." (PMID 25256700, 2014). "However, high and sustained levels of TNF-α can lead to neuronal damage, and there is evidence that TNF-α contributes to a variety of brain pathologies, such as ischemic stroke, Alzheimer’s disease, Parkinson’s disease, and multiple sclerosis." (PMID 24911209, 2014). "AD, Alzheimer’s Disease; Aβ, amyloid beta; APP, amyloid precursor protein; GFAP, glial fibrillary acidic protein; Iba1, ionized calcium binding adaptor molecule 1; PSD95, postsynaptic density protein 95; TNFα, tumor necrosis factor α." (PMID 22673542, 2012). "Several reports have shown a marked up-regulation of TNF expression under pathological conditions such as infection with Gram negative bacteria, Alzheimer's disease, Parkinson's disease and even brain inflammation." (PMID 16987412, 2006). "TNF-upregulation related necroptosis mediated by RIPK1 promotes further cell death and neuroinflammation in the pathogenesis of several neurodegenerative diseases including multiple sclerosis, amyotrophic lateral sclerosis (ALS), Parkinson disease and Alzheimer disease." (PMID 37996860, 2023). "A study on Alzheimer’s disease showed that EA at GV20 and EX-HN3 acupoints could effectively improve the learning and memory of mice and reduce the expression of interleukin-1β (IL-1 β), interleukin-6 (IL6), and tumor necrosis factor-α (TNF-α)." (PMID 37304438, 2023). "However, in a meta-analysis, compared with controls, only IL-1β was significantly elevated in Alzheimer’s disease but not IL-6, TNF-α or CRP and the significance did not survive Bonferroni-correction." (PMID 37467176, 2023). "In vivo studies using conventional TNF or TNFR knockout mice, or TNF inhibitors, showed neurotoxic roles for solTNF and TNFR1 in a wide range of experimental models including ischemia-reperfusion retinal damage, spinal cord injury, Parkinson’s disease, Alzheimer’s disease, and MS." (PMID 34565380, 2021).
Alzheimer disease (continued). "Two murine anti-tau antibodies (IgG gamma 1), named A and D, recognizing the 50–65 kD PHF triplet banding pattern, which is classical in Alzheimer’s disease and an isotype antibody recognizing the human TNFα but not murine TNFα (negative control antibody) were used for immunization study." (PMID 31038156, 2019). "However, elderly with Alzheimer’s disease only had significantly higher peripheral levels of IL-1β (p = 0.047) but not IL-6 (p = 0.138), TNF-α (p = 0.735) or CRP (p = 0.0712)." (PMID 30104698, 2018). "In comparison to non-transgenic controls, triple transgenic Alzheimer’s disease mice had increased total numbers of infiltrating peripheral monomyelocytic/granulocytic leukocytes with enhanced intracytoplasmic tumor necrosis factor-α, which was reduced after treatment with 3,6′-dithiothalidomide." (PMID 22632257, 2012). "Similarly, in middle-aged rats, neither synthetic nor human/patient brain-derived Aβ facilitated LTD in the presence of etanercept, leading us to conclude that TNF-α could serve as a critical mediator of LTD-facilitating effects of tau and Aβ present in Alzheimer’s disease brain aqueous extracts." (PMID 39391333, 2024). "Furthermore, memory impairment in the double-transgenic animal model of Alzheimer's disease is independent of hippocampal neuronal volume, and is completely reversed by inhibiting innate immune cytokines, namely interleukin-1, and TNFα." (PMID 27891071, 2016). "MaR1 promoted inflammation resolution by inhibiting chemotaxis, TNFα, IL1β, IL18 levels and NLRP3 inflammasome or NF-kB activation and regulating microglia activation in rodent models of Alzheimer’s disease, non-compressive lumbar disc herniation or inflammatory pain." (PMID 36670960, 2022). "TNF-α was an exception, in that the level did not correlate with EDN1 in the absence of infection; however, in cases with terminal infection, TNF-α showed a weak negative correlation with EDN1 in BS0–II disease and a strong positive correlation in advanced Alzheimer’s disease (BSV–VI)." (PMID 33723589, 2021). "Because there were no group differences in TNF-α or JNK-levels, we could not reproduce the TNF-α/JNK interrelations in Alzheimer’s disease in our mice." (PMID 26090621, 2015). "While we included leptin, IL-6, IL-1β, TNF-α, and CRP, we did not assess other cytokines such as MCP-1, IL-18, or markers of microglial activation and phenotype (e.g., CD68 and sTREM2), which may play significant roles in glial reactivity in Alzheimer's disease." (PMID 40521397, 2025).
colorectal cancer (516 papers, 1998 to 2026). A primary or metastatic malignant neoplasm that affects the colon or rectum. "Both sporadic and colitis-associated colorectal cancers have been found to have elevated TNF-α levels, which makes them an important target for therapeutic intervention." (PMID 40558596, 2025). "Patients with colorectal cancer often have elevated levels of IL-1β, IL-6, and TNF-α, which are associated with aggressive tumor behavior and a poor prognosis." (PMID 41463421, 2025). "Elevated levels of TNF-α have been associated with cancer progression and metastasis, particularly in colorectal cancer." (PMID 40699763, 2025). "A number of malignancies have high TNF- levels associated with metastasis, including colorectal cancer." (PMID 41476448, 2025). "For example, studies have reported that anti-TNF agents not only alleviate inflammation but also decrease the incidence of certain inflammation-associated malignancies, such as colorectal cancer in patients with IBDs." (PMID 40507276, 2025). "Additional studies have reported that inflammatory markers such as IL-1β, IL-6, and TNF-α are strongly associated with F. nucleatum infection and are more highly expressed in colorectal cancers harboring this bacterium." (PMID 41267807, 2025). "TNF-a: It is an important pro-inflammatory factor that plays a crucial role in the advancement and growth of colorectal cancer linked to colitis." (PMID 38717677, 2024). "Downregulation of TNFRSF1B (a member of the tumor necrosis factor gene family) in association with colorectal cancer here is consistent with prior studies showing lower mRNA expression of TNFRSF1B in lung cancer compared with normal lung tissue." (PMID 39227979, 2024). "MUC13 was demonstrated to enhance TNF-induced NF-κB activation, subsequently triggering the pathway and protecting colorectal cancer cells from apoptosis, with its high expression associated with tumor progression and metastasis." (PMID 39309442, 2024). "MiR-21 has been shown to be upregulated and co-associated with TNF-α expression in colorectal cancer and is positively associated with the progression of a metastatic phenotype." (PMID 36765584, 2023). "TNF-α was evaluated in four reports and found to associate with pre-treatment phenotypic and deficit accumulation frailty in colorectal cancer." (PMID 37213604, 2023). "On the contrary, recent observational studies have reported negatively on this risk and instead suggested that anti-TNFα mAb acts as a tumor suppressor in inflammatory carcinogenesis models and subcutaneous transplant models of colorectal cancer." (PMID 36996146, 2023). "Increased expression of IL‐1β and TNF‐α was also implicated in colorectal cancer development and progression." (PMID 37341064, 2023). "Examples of CRC related Gene Ontology also associated with colorectal cancer were GO:0005021 (vascular endothelial growth factor receptor activity) and GO:0032720 (negative regulation of tumor necrosis factor production)." (PMID 36593457, 2023). "No randomized controlled trials or prospective observational studies were performed to study the association between TNF inhibition and the risk of colorectal cancer." (PMID 36618924, 2022). "Fourth, during the development of NAFLD, the low inflammatory state caused by TNF-α and IL-6 leads to the disorder of gut microbiota, which can also initiate colorectal cancer." (PMID 36438843, 2022). "Tumor necrosis factor-alpha is associated with colorectal cancers via inducing the expression of VEGF." (PMID 36742002, 2022). "Our study, which adopted the mendelian randomization design—utilizing the random allocation of effect alleles, supported that genetically proxied TNF inhibition reduced the risk of colorectal cancer." (PMID 36618924, 2022).
colorectal cancer (continued). "We searched Pubmed and Web of Science from the database inception to 1 March 2021, for studies published in English or Chinese investigating the associations between tumor necrosis factor (TNF) levels or TNF inhibition and the risk of colorectal cancer." (PMID 36618924, 2022). "We selected the level of CRP as a biomarker to measure the effect size of TNF inhibition on the risk of colorectal cancer, instead of the level of TNFR1, based on previously published literature." (PMID 36618924, 2022). "The degree of differentiation was found to be an independent risk factor connected to TNF- α levels of patients with colorectal cancer." (PMID 36226059, 2022). "The instrument of TNF-inhibition was associated with a significantly lower risk of colorectal cancer, and the results showed an absolute risk reduction of 2.1% (the IVW analysis, 95%CI 0.4%–3.8%, p = 0.012) per 1 mg/L reduction in CRP." (PMID 36618924, 2022). "By using these cis-variants as proxies for TNF inhibition, we finally found that TNF inhibition was associated with a 2.1% absolute risk reduction in colorectal cancer per 1 mg/L decrease in CRP." (PMID 36618924, 2022). "In another study of 173 IBD-associated colorectal cancer patients from 78 hospitals, anti-TNF therapy was associated with a significant protective effect against CRC development (OR, 0.09, 95% CI, 0.01–0.68, p = 0.02)." (PMID 36618924, 2022). "We found that the anti-TNF effect was associated with an absolute risk reduction in the risk of colorectal cancer (-2.1%, 95%CI -3.8% to -0.4%, p = 0.01) per 1 mg/L reduction in serum C-reactive protein." (PMID 36618924, 2022). "We adopted the drug-target MR design and used data from large-scale genome-wide association studies (GWASs), to examine the impact of the genetically proxied TNF inhibition on the risk of colorectal cancer." (PMID 36618924, 2022). "The cytokines IL-1β and TNF-α are strongly associated with inflammation-driven cancers, including colorectal cancer, and contribute to tumor growth and invasion." (PMID 34361836, 2021). "On the other hand, we identified 121 upregulated predicted gene targets for downregulated miRNAs, which were linked to metabolic pathways, TNF signaling, IL-17 signaling, and genes associated with colorectal cancer." (PMID 34642361, 2021). "Inflammation and TNF-α expression is associated with many different tumor types including colorectal cancer." (PMID 33961948, 2021). "Given the importance of TNF in colorectal cancer progression, the polymorphisms of TNF rs361525 G > A and rs1800629 G > A were shown to correlate with the risk of CRC in Caucasians and Asians." (PMID 33917839, 2021). "Increased levels of TNFα and IL-6 were detected in tumor tissues and sera of patients with colorectal cancer, and these cytokines were associated with increased tumor burden and tumor staging, metastasis, and lower overall survival." (PMID 32317968, 2020). "Although this does not provide causal evidence, in genetic studies polymorphisms of TNF have been associated with colorectal cancer risk." (PMID 32805626, 2020). "In the case of colorectal cancer, the proinflammatory cytokines IL-1β, IL-6, IL-8, IL-12, IL-17, and tumor necrosis factor-α (TNF-α) can be associated with the development of cancer." (PMID 33374549, 2020). "There is evidence of TNF’s role in promoting regression of unresectable hepatic metastasis from colorectal cancer and in causing tumour necrosis via its pro-coagulant effect." (PMID 31381571, 2019). "Increased levels of TNF-α are associated with metastatic disease in several cancer types including colorectal cancer." (PMID 30999696, 2019). "Baseline plasma TNFRSF1B, a marker of inflammation and a soluble TNF antagonist, was significantly associated with an increased risk of human colorectal cancer." (PMID 30061500, 2018).